NDUFAF5 (NADH:ubiquinone oxidoreductase complex assembly factor 5)
Description:
Arginine hydroxylase that mediates hydroxylation of 'Arg-111' of NDUFS7 and is involved in the assembly of mitochondrial NADH:ubiquinone oxidoreductase complex (complex I, MT-ND1) at early stages. May also have methyltransferase activity (Probable).
Synonyms: C20orf7; dJ842G6.1; MC1DN16; bA526K24.2
Tractability: PROTAC: ubiquitination databases record sites on it; its protein half-life has been measured.
Gene: Protein-coding gene on chromosome 20 (13,785,007 to 13,821,580, forward strand). Ensembl gene ENSG00000101247.
Subcellular location: Mitochondrion inner membrane
Pathways (Reactome):
Metabolism: Complex I biogenesis
Gene Ontology:
Molecular function: protein binding; S-adenosylmethionine-dependent methyltransferase activity
Biological process: mitochondrial respiratory chain complex I assembly
Cellular component: matrix side of mitochondrial inner membrane; mitochondrial inner membrane; mitochondrion
Genetic constraint (gnomAD): Loss-of-function variants: 19 observed, 26.11 expected, observed/expected ratio (o/e) 0.73, 90% interval 0.51 to 1.07. The upper end of that interval is the gene's LOEUF score, 1.07, which puts it in group 4 of 6, group 1 being the genes least tolerant of losing a copy. Missense variants: 298 observed, 299.79 expected, observed/expected ratio (o/e) 0.99, 90% interval 0.9 to 1.09. Synonymous variants: 115 observed, 113.18 expected, observed/expected ratio (o/e) 1.02, 90% interval 0.87 to 1.19.
Gene-disease validity (ClinGen):
ClinGen rates the evidence that NDUFAF5 causes each of these diseases.
Leigh syndrome (autosomal recessive): Definitive. A progressive neurological disease defined by specific neuropathological features associating brainstem and basal ganglia lesions.
mitochondrial disease (autosomal recessive): Definitive.
Homologues: Orthologues: chimpanzee NDUFAF5 (99% identical), macaque NDUFAF5 (94% identical), dog NDUFAF5 (91% identical), pig NDUFAF5 (88% identical), rabbit NDUFAF5 (88% identical), guinea pig NDUFAF5 (87% identical), mouse Ndufaf5 (84% identical), rat Ndufaf5 (84% identical), tropical clawed frog ndufaf5 (65% identical), zebrafish ndufaf5 (62% identical), Drosophila melanogaster CG8067 (47% identical), Caenorhabditis elegans K09E4.3 (44% identical).
Diseases named in the same sentence as NDUFAF5 in open-access papers:
NDUFAF5 is named in the same sentence as 25 diseases in open-access papers, as found by Europe PMC text mining. Sharing a sentence is not in itself a finding about the gene and the disease. The quoted sentences say what the papers report.
Leigh syndrome (5 papers, 2018 to 2025). "Previously, it has been reported that mutations in NDUFAF5 are associated with Leigh syndrome due to attenuated ETC Complex I assembly." (PMID 40332450, 2025). "Mutations in NDUFAF5 were found to be related to cavitating leukoencephalopathies, lactic acidosis, classic Leigh syndrome, hyponatremia and some lethal neonatal mitochondrial diseases 41-43." (PMID 33403043, 2021). "In line with previously reported complex I deficient patients, we found that defects in NDUFS7, NDUFA12, and NDUFAF5 caused Leigh-syndrome or a Leigh-like-phenotype." (PMID 30369941, 2018). "Defects in NDUFS7, NDUFA12 and NDUFAF5 caused Leigh-syndrome or a Leigh-like-phenotype." (PMID 30369941, 2018). "Our findings revealed two novel variants in the NDUFAF5 and FASTKD2 genes, which were associated with the development of Leigh syndrome and Leigh-like syndrome, respectively." (PMID 38283147, 2023).
COVID-19 (2 papers, 2020 to 2023). A disease caused by infection with severe acute respiratory syndrome coronavirus 2. "Several mitochondrial genes, for instance NDUFA10, NDUFAF5, and SAMM50 were downregulated in COVID-19-affected lung." (PMID 33173052, 2020).
Dystonia (2 papers, 2021 to 2025). An abnormally increased muscular tone that causes fixed abnormal postures. "And the NDUFAF5-related BSN pathology should be included in the differential diagnosis of patients presenting with insidious dystonia in early childhood that progresses from gait disturbances to generalized dystonia with dysphagia and dysarthria." (PMID 34177781, 2021).
arterial hypertension (1 paper, 2019). "Since arterial hypertension has been repeatedly reported as a primary manifestation of mitochondrial disorders (MIDs), it is conceivable that arterial hypertension in patient-1 as well as patient-3 was a primary phenotypic manifestation of the NDUFAF5 mutation." (PMID 30581749, 2019).
developmental delay (1 paper, 2022). "Pathogenic variants in NDUFAF5 have been associated with an early-onset complex I deficiency, characterized by developmental delay, failure to thrive, hypotonia, and seizures, in agreement with the clinical presentation of the investigated individual." (PMID 35379322, 2022).
situs inversus (1 paper, 2026). A congenital condition in which there is complete right-to-left reversal of the position of the major thoracic and abdominal organs (that is, they are arranged in a mirror image of the normal positioning). "In this case, genetic testing identified likely pathogenic variants in LAMA2 and NDUFAF5, neither of which is associated with laterality defects, suggesting the patient's situs inversus is likely idiopathic." (PMID 41788120, 2026).
NDUFAF5 also shares sentences with these, for which no sentence is quoted: mitochondrial disease (3 papers); cancer (2); neurological diseases (2); autosomal recessive disease (1); cardiac arrest (1); colon cancer (1); Failure to thrive (1); generalized dystonia (1); glutaric acidemia (1); Hyponatremia (1); lactic acidosis (1); leukoencephalopathies (1); lung carcinoma (1); mitochondrial complex I deficiency (1); neoplasm (1); neuroblastoma (1); optic atrophy (1); retinal degeneration (1); Schaaf-Yang syndrome (1).